CCL5 (C-C motif chemokine ligand 5)
Diseases named in the same sentence as CCL5 in open-access papers (continued):
Sharing a sentence is not in itself a finding about the gene and the disease.
cancer (continued). "We recently reported that cancer Forkhead box protein 3 (Cancer-FOXP3 or C-FOXP3) promoted immune evasion of PDAC by recruiting Treg cells into PDAC via upregulation of CCL5." (PMID 32300119, 2020). "Meanwhile, a study identified that zoledronic acid can significantly affect the interaction between Tregs and cancer cells by reducing the expression of CCL5 and CCL259." (PMID 33173412, 2020). "CCL5 was directly transactivated by cancer-Foxp3 and promoted the recruitment of Tregs from peripheral blood to the tumour site." (PMID 32680511, 2020). "CCL5/CCR5 interactions have also been shown to promote cancer cell migration, possibly by upregulating MMP production." (PMID 32992699, 2020). "Since stimulation of the CCR5/CCL5 interaction induces the proliferation of various cancer cells, we determined if inhibition of the interaction would lead to apoptosis of HCC cells." (PMID 32260550, 2020). "It has been reported that the CCL5/CCR5 axis influences cancer cell proliferation, invasion and the establishment of an immunosuppressive microenvironment." (PMID 32784743, 2020). "The chemokine CCL5, originally termed RANTES (regulated on activation, normal T cell expressed, and secreted) is a CC chemokine ligand 5, both known for his role in inflammatory diseases and cancer progression." (PMID 32545571, 2020). "Cancer cells secrete CCL5 or they induce adjacent fibroblasts to secrete CCL5, which ensures the proliferation of CCR5-positive cells." (PMID 32260550, 2020). "This is important in cancer because the CCL5/RANTES→CCR5 axis is of great importance in the growth of tumors." (PMID 32781743, 2020). "Cancer cells secrete chemokine (C-C motif) ligand 5 (CCL5) to attract immunosuppressive Tregs, C-X-C motif chemokine 5 (CXCL5) to recruit neutrophils and colony-stimulating factor-1 (CSF-1) to attract macrophages." (PMID 32397303, 2020). "Increased expression levels of CCL5 mRNA and protein were observed in prostate cancer tumor tissues than para-carcinoma tissues, accompanied by the decreased expression of E-cadherin and increased expression of Vimentin." (PMID 32300100, 2020). "It is therefore likely that the increased co-expression of CXCR4 and CCR5 in RhoA knockdown cancer cells facilitates the recruitment of CXCL12/CCL5 secreting CAFs and later the TAMs into the TME." (PMID 31705019, 2019). "CAFs are also involved in endometrial carcinogenesis due to their secretion of IL-6, IL-8, MCP-1, CCL5, and RANTES to promote cancer progression." (PMID 30935077, 2019). "The CAFs then promote cancer cells invasion and proliferation by secreting several chemokines and cytokines including C-C motif chemokine ligand 5 (CCL5), which is a direct target of miR-214." (PMID 31640297, 2019). "In breast cancer, the cancer cells stimulate the secretion of CCL-5 from MSCs, which acts in a paracrine fashion on the cancer cells to enhance their motility, invasion, and metastasis." (PMID 31417869, 2019). "It has been shown in various cancer types that the CCL5/CCR5 chemokine/receptor axis is hyperactivated and involved in multiple phases of carcinogenesis, including proliferation, migration, invasion, angiogenesis, and metastatic colonization." (PMID 31505877, 2019). "The expression of CCR5, the cognate receptor for CCL5 was likewise found to be upregulated in RhoA knockdown 4T1 cancer cells." (PMID 31705019, 2019). "Other models propose blockade of immune cell homing to cancer tissue by barrier molecules, chemo-inhibitory mechanisms, and by epigenetic silencing of chemokines (CCL5, CXCL9, and CXCL10), Th1 signaling molecules and antigen processing machinery components." (PMID 29871670, 2018). "ASPP2 also induced C−C motif chemokine ligand (CCL) 2, CCL5, and tumor necrosis factor-α secretion by cancer cells, thereby promoting macrophage recruitment." (PMID 30389910, 2018).
cancer (continued). "Another therapeutic modality that deserves some consideration deals with the possibility to counteract the cross talk mediated by the CCL5/CCR5 axis between cancer cells and MSCs." (PMID 29772686, 2018). "The scientific literature describe a dual role for CCL5 in cancer, attributing it a good outcome or a poor outcome role." (PMID 29559701, 2018). "Molecular method was based on the analysis of selected genes expression related to hypoxia (HIF1A, ANGPTL4, TGFB1, VEGFA, ERBB3, CA9) or specific for inflammation in hypoxic sites (CCL2, CCL5) at various time points after CT26 cancer cells inoculation." (PMID 30412628, 2018). "Pritchard, M.T and Roberson, R.16,17 reported that alcohol stimulated cancer cells to secrete variety of cytokines and chemokines, including some inflammatory cytokines and CCL5." (PMID 29872080, 2018). "It is evident from previous reports that CCR5 and CCL5 are responsible for cancer progression and metastasis." (PMID 29358632, 2018). "CCL5 belongs to the CC-chemokine family and plays a critical role in the migration and metastasis of human malignant tumor cells." (PMID 29844932, 2018). "Herein, we show that cordycepin prevents constitutively Akt-mediated NF-κB transcription factor activation by downregulating CCL5 and that the consequent activation of JNK signaling pathway causes cancer cell death." (PMID 29844932, 2018). "Proliferation, angiogenesis, and metastasis are all important to cancer progression, and it has been reported CCL5 contributes to these processes." (PMID 29872080, 2018). "Increased levels of CCR5 and CCL5 have established indicators for disease status in various cancers, including PC." (PMID 29358632, 2018). "The treatment of cordycepin (100 μg/mL) significantly suppressed the cell migration in both CCL5-overexpressed and control vector-transfected cancer cells in a dose-dependent manner at 48 h." (PMID 29844932, 2018). "CCL5 is a proinflammatory chemokine involved in inflammatory cell recruitment, cancer‐related angiogenesis, and tumor metastasis formation." (PMID 28599100, 2017). "Our study provides evidence that ANXA1 modulates TAM function and phenotype through FPR2-ERK signalling, involving CCL5 in the microenvironment, suggesting a potential new axis for targeting cancer therapy." (PMID 29263330, 2017). "Our previous reports demonstrated that CCL5 contributed significantly to cancer metastasis under hypoxia." (PMID 29299159, 2017). "By focusing on the role of the chemokine CCL5 (which has been reported to be related to cancer migration and metastasis in other cancers as well as), they reported that CCL5 induces VEGF upregulation." (PMID 28272374, 2017). "MD-231 CM significantly increased the production of CCL5 in THP-1 macrophages; inhibition of LDHA greatly attenuated cancer cell-induced CCL5 secretion." (PMID 29299159, 2017). "To investigate the role of CCL5-CCR5 axis in macrophage-induced cancer aerobic glycolysis, we inhibited CCL5 secretion in the co-culture system using anti-CCL5 neutralizing antibody." (PMID 29299159, 2017). "Inhibition of CCR5, the cognate receptor of CCL5, or neutralization of CCL5, broke the metabolic loop and decreased cancer cell migration and EMT." (PMID 29299159, 2017). "Other research has shown that mesenchymal stem cells secrete CCL5 promoting cancer cell motility, invasion, and metastasis." (PMID 28693495, 2017). "CCL5 has a similar effect on cancer cell migration, while Maraviroc (20 μM) has an opposite effect (P < 0.05)." (PMID 29088737, 2017). "Interruption of this interaction between CCL5 and CCR5 by knocking down CCL5 in cancer cells that were used for cancer cell transplantation in mice impedes cancer growth." (PMID 29379802, 2017). "Then we cultured cancer cell with different concentration of MSC(TI)-CM along with CCL5 neutralizing antibody (0.5 μg/ml)." (PMID 29088737, 2017).
cancer (continued). "CCL5 is a chemokine that boosts cancer progression by arousing and adjusting the inflammatory diseases, which sequently reconstruct the cancer microenvironment." (PMID 29170526, 2017). "CCL5 is expressed in T lymphocytes, macrophages, platelets, synovial fibroblasts and some types of cancer cells." (PMID 29299159, 2017). "The virus behaves as a potent oncolytic virus in human and murine cancer cells and produces a high level of secreted CCL5 from infected human cells." (PMID 29085848, 2017). "These opposite effects appear to be justified by the type of cancer, CCR5 expression by cancer cells, and localization of CCL5 expression." (PMID 29375583, 2017). "From human cancer microarray data obtained from the OncomineTM Platform database, IL-8 and CCL-5 were shown to be up-regulated in ccRCC patients." (PMID 28572533, 2017). "One potential explanation is that the expression levels of CCL5, an important chemokine for cancer cells metastasis and macrophage infiltration, were not affected in CAFs-TM compared to CAFs-Scr." (PMID 27541266, 2016). "It has been recently emerged that BM-MSCs recruited to tumors secrete the chemokine CCL5 (also called RANTES), which acts in a paracrine fashion to suppress AR signaling in neighbouring cancer cells." (PMID 26880966, 2016). "Our study is the first to report that chemokine CCL5 induces lymphangiogenesis by the induction of VEGF-C in human cancer cells." (PMID 27166194, 2016). "Further work is needed to analyze the association between CCL5 and IGF-1 staining in adipose tissue and cancer features of patient with ER positive cancer." (PMID 27027351, 2016). "And CD133+ cancer cells were reported to be related with the chemokine CCL5, so we also attempted to combine CXCL9 with the CD133+ cancer cells." (PMID 26883105, 2016). "The secreted CCL5 can act in an autocrine, paracrine or juxtacrine manner to advance processes crucial for cancer development." (PMID 26375811, 2015). "Our results showed that neutralization of CCL5 reduced the number of invasive cancer cells in a dose-dependent manner (p<0.05)." (PMID 25788271, 2015). "CCL5 belongs to the CC-chemokine family and plays a pivotal role in the invasion and metastasis of human cancer cells." (PMID 25907256, 2015). "The CCL5 secreted from BM-MSCs can increase the cancer stem cell and EMT markers, such as the CD133, ZEB-1 and CXCR4." (PMID 26342197, 2015). "Among the chemokines differentially affected by MDA-MB-231 and MCF-7 CM, CCL5 has previously been shown to be induced in MSCs stimulated by cancer cells." (PMID 26362269, 2015). "Next, to assess the role of CCL5 on cancer cell invasion, we added neutralizing CCL5 antibodies or a control antibody into CM derived from wild-type and JDP2 −/− BMDCs." (PMID 26497998, 2015). "While restoration of RKIP in low-RKIP-expressing invasive cancer cells suppressed CCL5 expression and inhibited invasion, silencing of RKIP in high-RKIP-expressing non-invasive cells increased CCL5 expression." (PMID 26375811, 2015). "RKIP expression favors the existence of a more subdued microenvironment for cancer cells by suppressing the expression of chemokine CCL5 and subsequent inhibition of active macrophages recruitment into the tumors." (PMID 26375811, 2015). "Overall, our current knowledge leads us to suggest the CCL5/CCR5 axis as a potential therapeutic target in several cancer diseases." (PMID 24523569, 2014). "Since this cytokine has been previously suggested to be a factor related to cancer cell invasion, we next investigated the role of CCL5 in the cancer cell invasion assay." (PMID 25271422, 2014). "While most combinations of these receptors and chemokines are active in cancer, many findings in the field have emphasized the chemokine CCL5 and its cognate receptor CCR5." (PMID 24822066, 2014).
cancer (continued). "We have also shown that the chemokine CCL5-expressing oncolytic VV in combination with a cancer vaccine or activated T cells resulted in better therapeutic effect in a MC38 colon cancer model." (PMID 24782985, 2014). "It is known that the chemokine CCL5 is highly expressed in cancer where it contributes to inflammation and malignant progression, but the question of which cancer cell-derived chemokines are friends and which are enemies remains unanswered." (PMID 24591756, 2014). "Down-regulation of CCL5 is in line with several studies in human cancers, however contradictory to others." (PMID 24886914, 2014). "A clear association has been described between the CCL5/CCR5 axis and the directional migration and invasion of human cancer cells." (PMID 23157946, 2012). "We found up-regulation of the highly potent macrophage attracting factors: CCL2 (MCP-1), CCL3 (MIP-1α), CCL4 (MIP-1β) and CCL5 (RANTES) as well as CCR5 in cancer cells grown as co-culture with macrophages." (PMID 22353646, 2012). "Interaction of CCL5 with its specific receptor CCR on the surface of cancer cells has been reported to induce cancer migration." (PMID 22506069, 2012). "This was further confirmed by the result that the cyclic RGD inhibited the enhancement of migration activity by CCL5, indicating the involvement of αvβ3 integrin in CCL5-mediated induction of cancer migration." (PMID 22506069, 2012). "Interaction of CCL5 with its specific receptor CCRs on the surface of cancer cells has been reported to induce cancer invasion." (PMID 22506069, 2012). "Similar in vitro studies, employing conditioned media derived from stromal cells, have shown that stromal cells secrete SDF-1 and CCL5, which promote cancer cell proliferation and invasion." (PMID 20637104, 2010). "CCL5 is involved in the occurrence, development and metastasis of various cancers." (PMID 40396123, 2025). "Disrupting the circ-DHPS/miR-214-3p/CCL5 interaction may offer a strategy to reduce the migration of cancer cells." (PMID 40556678, 2025). "Furthermore, its overexpression promoted macrophage polarization towards the M2-like phenotype and promoted the migration of M2-like macrophage cells and C-C Motif Chemokine Ligand 5 (CCL5) was the key mediator in the pro-cancer effect of SECTM1." (PMID 39944684, 2025). "Also, inflammation is involved in cancer proliferation and multiple pro-inflammatory cytokines (e.g., CCL5, CX3CL1, and CXCL12) play a role in cancer." (PMID 40943574, 2025). "C/EBPβ and STAT3 expression negatively correlates with CCL5 across multiple human tissues, while elevated C/EBPβ/STAT3 expression is associated with reduced CD8+ T cell infiltration and poor survival across various cancer types." (PMID 40749055, 2025). "CCR5 and its ligand CCL5 have been involved in cancer progression." (PMID 39827154, 2025). "CCL5, also called RANTES, plays multifaceted roles in cancer." (PMID 40282185, 2025). "Chemokine CCL5 increases cancer stemness features, and STAT3 and PI3K/AKT activation." (PMID 40683954, 2025). "However, the short half-life of CCL5 limits its effectiveness as a cancer therapy, and the introduction of oncolytic viruses can effectively address this issue." (PMID 40295404, 2025). "In addition to CCL2, CCL22, and IL-10, TAM-associated markers CCL5 and SPP1 (secreted phosphosprotein 1, also known as osteopontin, OPN) are promising targets for novel cancer immunotherapy." (PMID 40806751, 2025). "Additionally, eosinophils stimulate the proliferation of natural killer (NK) cells and facilitate the CCL5-dependent recruitment of NK cells to the lungs in mice, contributing to anti-cancer effects." (PMID 40703295, 2025). "In addition, cancer cells can stimulate CD4+ T cells to secrete CCL5, inducing Fas-mediated apoptosis of CD8+ T cells." (PMID 39114657, 2024).
cancer (continued). "Interestingly, most genes were up-regulated in multiple groups; genes for chemokines (Ccl2, Ccl5), cell adhesion (Icam1, Lgals3) and a growth factor (Ngf) were up-regulated in at least three non-cancer groups." (PMID 39254423, 2024). "In addition, cancer-associated adipocytes have been found to release high levels of cytokines and growth factors such as IL-6, CCL2, CCL5, IL1β, TNFα, and VEGF, which collectively contribute to enhanced tumor cell proliferation, invasion, and angiogenesis." (PMID 38800384, 2024). "In addition, CCL5 has direct protumoral effects on cancer cells, promoting cancer proliferation and metastasis." (PMID 38722600, 2024). "Moreover, the co-culture of ECs with breast cancer cells leads to EMT-controlled cancer cell migration, invasion, and metastasis, which were enhanced when CCL5, from ECs, binds to CCR5, a chemokine receptor of cancer cells." (PMID 38244071, 2024). "In contrast, CCL5 and CXCL9 expression in Pa and LM4 cancer cells was compared at the mRNA level to confirm whether CCL5 and CXCL9 are secreted by cancer cells in vitro." (PMID 39126553, 2024). "Given the critical role of CCL5 in cancer cell activity and its high affinity for the receptor CCR5, we investigated whether targeting the CCL5–CCR5 axis could be an effective strategy in PDAC treatment using maraviroc, a selective CCR5 antagonist." (PMID 39261943, 2024). "In addition to CCL5 expression, high CXCL11 expression levels were noted to be associated with a poorer prognosis in most cancers." (PMID 37627528, 2023). "The selected haplotypes for CCL5 and CCL2 SNPs also correlated with an increased risk of cancer." (PMID 38001676, 2023). "CCL5 is a member of the CC chemokine family because it has two pairs of adjacent cysteine residues near the amino terminus and is expressed and secreted by macrophages, T cells, tubular epithelial cells, synovial fibroblasts and certain types of cancer cells." (PMID 37141250, 2023). "Our experiments in vitro confirmed the ability of poly(I:C)+R848-prot-NCs, with or without HA-mannose coating, to stimulate macrophages towards an M1-like antitumoral mode, characterized by secretion of CXCL10 and CCL5 and also increased cytotoxic activity towards cancer cells." (PMID 38259462, 2023). "Reports published so far on the role of RANTES/CCL5 in cancer have been controversial." (PMID 36983384, 2023). "The expression level of CCL5 is related to the growth and metastasis of many kinds of cancers, including CRC, and CCL5 not only plays an important role in the progression of CRC but can also be used to evaluate the curative effect of treatment and for diagnostics." (PMID 37141250, 2023). "The role of CCL5 in sustaining cancer progression is well-established." (PMID 36765778, 2023). "These signals include chemokines, with CCL5 involved in many mechanisms of cancer progression, including cell proliferation, migration, invasion, angiogenesis, metastasis and colonization and the regulation of the extracellular matrix and immune escape mechanism of cancer, as signaling." (PMID 37141250, 2023). "On the contrary, CCL5 (a key T cell chemokine) is commonly upregulated in all cancers." (PMID 37024957, 2023). "Other mediators of cancer stemness intersect with CCR5/CCL5 signaling." (PMID 37759462, 2023). "Collectively, these studies suggest important mechanisms by which CCR5/CCL5 may augment cancer stem cell expansion and the TME to induce a pro-tumorigenic environment." (PMID 37759462, 2023). "CCL5 also promotes angiogenesis, which is associated with an increase in vascular endothelial growth factor (VEGF) expression in cancer cells and vascular endothelial cells via the activation of C-C Motif Chemokine Receptor 1 (CCR1) and C-C Motif Chemokine Receptor 5 (CCR5)." (PMID 37895310, 2023). "Targeting the CCL4 and CCL5 pathways may offer new strategies for controlling cancer metastasis and improving treatment outcomes in TSCC." (PMID 38067251, 2023).